DTNBP1 (dystrobrevin binding protein 1)
Description:
Component of the BLOC-1 complex, a complex that is required for normal biogenesis of lysosome-related organelles (LRO), such as platelet dense granules and melanosomes. In concert with the AP-3 complex, the BLOC-1 complex is required to target membrane protein cargos into vesicles assembled at cell bodies for delivery into neurites and nerve terminals. The BLOC-1 complex, in association with SNARE proteins, is also proposed to be involved in neurite extension. Associates with the BLOC-2 complex to facilitate the transport of TYRP1 independent of AP-3 function. Plays a role in synaptic vesicle trafficking and in neurotransmitter release. Plays a role in the regulation of cell surface exposure of DRD2. May play a role in actin cytoskeleton reorganization and neurite outgrowth. May modulate MAPK8 phosphorylation. Appears to promote neuronal transmission and viability through regulating the expression of SNAP25 and SYN1, modulating PI3-kinase-Akt signaling and influencing glutamatergic release. Regulates the expression of SYN1 through binding to its promoter. Modulates prefrontal cortical activity via the dopamine/D2 pathway.
Synonyms: BLOC1S8; My031; Dysbindin; HPS7; DBND; SDY
Tractability: Antibody: UniProt places it where antibodies can reach, with high confidence; its Gene Ontology location is reachable by antibodies, with medium confidence. PROTAC: UniProt records ubiquitination sites on it; ubiquitination databases record sites on it; its protein half-life has been measured.
Safety:
Unwanted effects reported when the protein is acted on. In parentheses: how it was acted on, where the effect was seen, and who reports it.
methamphetamine psychosis (source: ClinPGx)
not studied (source: ClinPGx)
psychosis (source: ClinPGx)
Gene: Protein-coding gene on chromosome 6 (15,522,807 to 15,663,058, reverse strand). Ensembl gene ENSG00000047579.
Subcellular location: Cytoplasm (Isoform 1); Cytoplasmic vesicle membrane; Endosome membrane; Melanosome membrane; Postsynaptic density; Endoplasmic reticulum; Nucleus; Cytoplasm (Isoform 2); Cytoplasmic vesicle, secretory vesicle, synaptic vesicle membrane; Postsynaptic cell membrane; Cytoplasm (Isoform 3)
Subcellular location (Human Protein Atlas): Microtubules; Midbody
Pathways (Reactome):
Vesicle-mediated transport: Golgi Associated Vesicle Biogenesis
Gene Ontology:
Molecular function: protein binding
Biological process: neuron projection development; actin cytoskeleton organization; anterograde axonal transport; anterograde synaptic vesicle transport; melanosome organization; neuron projection morphogenesis; platelet dense granule organization; positive regulation of gene expression; positive regulation of neurotransmitter secretion; regulation of dopamine receptor signaling pathway; regulation of dopamine secretion; regulation of signal transduction; regulation of synaptic vesicle exocytosis; negative regulation of dendritic spine morphogenesis; positive regulation of glutamate neurotransmitter secretion in response to membrane depolarization; positive regulation of receptor internalization; retina development in camera-type eye
Cellular component: BLOC-1 complex; microtubule cytoskeleton; neuron projection; postsynaptic density; synaptic vesicle membrane; axon; cytoplasm; cytosol; dendritic spine; endoplasmic reticulum membrane; growth cone; nucleus; plasma membrane; sarcolemma; axon cytoplasm; cytoplasmic vesicle membrane; endoplasmic reticulum; endosome membrane; melanosome membrane; neuronal cell body; postsynaptic membrane
Genetic constraint (gnomAD): Loss-of-function variants: 34 observed, 41.03 expected, observed/expected ratio (o/e) 0.83, 90% interval 0.63 to 1.1. The upper end of that interval is the gene's LOEUF score, 1.1, which puts it in group 4 of 6, group 1 being the genes least tolerant of losing a copy. Missense variants: 442 observed, 424.23 expected, observed/expected ratio (o/e) 1.04, 90% interval 0.96 to 1.13. Synonymous variants: 170 observed, 162.81 expected, observed/expected ratio (o/e) 1.04, 90% interval 0.92 to 1.19.
Gene-disease validity (ClinGen):
ClinGen rates the evidence that DTNBP1 causes each of these diseases.
Hermansky-Pudlak syndrome 7 (autosomal recessive): Definitive.
Homologues: Orthologues: chimpanzee DTNBP1 (99% identical), guinea pig DTNBP1 (86% identical), pig DTNBP1 (83% identical), dog DTNBP1 (81% identical), macaque DTNBP1 (79% identical), mouse Dtnbp1 (78% identical), rat Dtnbp1 (77% identical), rabbit DTNBP1 (76% identical), tropical clawed frog dtnbp1 (69% identical), zebrafish dtnbp1a (64% identical), zebrafish dtnbp1b (32% identical), Drosophila melanogaster Dysb (22% identical), and 1 more. Paralogues in human: DBNDD2 (17% identical), DBNDD1 (15% identical).
Diseases named in the same sentence as DTNBP1 in open-access papers:
DTNBP1 is named in the same sentence as 61 diseases in open-access papers, as found by Europe PMC text mining. Sharing a sentence is not in itself a finding about the gene and the disease. The quoted sentences say what the papers report.
schizophrenia (102 papers, 2005 to 2026). A major psychotic disorder characterized by abnormalities in the perception or expression of reality. "Mutations in the DTNBP1 gene or reduction in its mRNA and protein levels are associated with a higher occurrence of schizophrenia." (PMID 41507144, 2026). "Specific polymorphisms of schizophrenia-related gene DTNBP1 (dystrobrevin-binding protein 1) were found to either increase or reduce the risk for TLE." (PMID 38927072, 2024). "In particular, DTNBP1 risk polymorphisms are more common in individuals with earlier adult-onset schizophrenia, characterized by pronounced cognitive deficits and clinical symptoms." (PMID 39684450, 2024). "The human ortholog DTNBP1 is reported to be associated with schizophrenia, responses to antipsychotic drugs as well as cognitive abilities in healthy individuals." (PMID 38956130, 2024). "Many promising candidate genes have been identified for schizophrenia susceptibility, of which the gene encoding dystrobrevin-binding protein-1 (dysbindin-1 or DTNBP1) has received considerable experimental attention." (PMID 39684450, 2024). "In humans, JARID2 is in close proximity to Dysbindin (DTNBP1), which is strongly associated with schizophrenia (SCZ)." (PMID 38203196, 2023). "The association of dysbindin-1 with schizophrenia causing primary pathology has been related with downregulation of DTNBP1 expression in dorsolateral PFC and HC formation." (PMID 36692676, 2023). "Allelic variation of DTNBP1 has been linked with schizophrenia causing white matter integrity impairments in healthy adult subjects, decrease in grey matter volume in preteenagers, anomalies in neurite outgrowth and morphology, resulting in cognitive deficits." (PMID 36692676, 2023). "Three paralogs are expressed in the brain, but dysbindin-1 has garnered the most attention due to polymorphisms in its encoding gene, DTNBP1, and controversies around its relationship with schizophrenia, and cognitive deficits." (PMID 37569304, 2023). "Dysbindin C-A-T haplotype (risk allele of DTNBP1 rs2619539, rs3213207, rs2619538) is associated with increased risk of schizophrenia and affects brain structure reducing grey matter volume." (PMID 36833173, 2023). "Genetic changes in the DTNBP1 gene, which encodes dysbindin-1 protein, have been implicated as a gene risk factor for schizophrenia development." (PMID 35682647, 2022). "Genome-wide association studies have identified multiple single nucleotide polymorphisms (SNPs) of DTNBP1 as potential risk factors for schizophrenia." (PMID 35815020, 2022). "Dystrobrevin-binding protein 1, also known as dysbindin, has been reported to be associated with schizophrenia." (PMID 35246634, 2022). "Taken together, these results indicate that DTNBP1 plays several important roles in regulating inhibitory transmission and pathogenic mechanisms of schizophrenia, at least in part via BDNF secretion." (PMID 35815020, 2022). "Several studies conducted in Japanese, Irish, and Chinese populations suggest that genetic variation in DTNBP1 is associated with schizophrenia." (PMID 35815020, 2022). "The null protein mutation of Dtnbp1 in sandy (sdy) mice displayed schizophrenia-like behaviors and deficits in dopaminergic, glutamatergic, and GABAergic neurotransmission." (PMID 35815020, 2022). "DTNBP1 variants in the prefrontal cortex are thought to contribute to the pathophysiology of schizophrenia through alterations in glutamatergic transmission." (PMID 34064652, 2021). "In this study, we present evidence that dystrobrevin-binding protein 1 (dysbindin), a schizophrenia-associated factor, plays a critical role in axonal mitochondrial movement." (PMID 33461576, 2021). "Another subset of genes involved in schizophrenia are those related to brain development, for example DTNBP1, encoding dysbindin." (PMID 34576069, 2021). "We review evidence describing how sequence variation in DTNBP1 isoforms has been differentially associated with schizophrenia-associated symptoms." (PMID 32063853, 2019).
schizophrenia (continued). "A recent study also demonstrated that human schizophrenia subjects with genetic variants in the gene that encodes dysbindin-1 (DTNBP1) exhibited cognitive dysfunction." (PMID 30967545, 2019). "It will be interesting for future studies to use cell cultures to determine if humans with schizophrenia and dysbindin-1 (DTNBP1) mutations have altered homoeostatic or inflammation-induced immune responses." (PMID 30038210, 2018). "DTNBP1 is found at chromosomal locus 6p22.3 and mutations on this locus have been linked to schizophrenia." (PMID 28937620, 2017). "Deletion in the DTNBP-1 gene causes reduced level of snapin, which is accompanied by defects of synaptic morphology in hippocampal neurons and schizophrenia-like behaviors in mice." (PMID 28937620, 2017). "Many studies have shown that dystrobrevin binding protein-1 (dysbindin-1) is one of the important potential susceptibility genes for schizophrenia." (PMID 28937620, 2017). "Clinical studies provide some evidence indicating potentially significant associations between DTNBP1 gene variation and the impact of adverse environmental risk factors on risk to develop schizophrenia." (PMID 27725886, 2016). "Among these candidate genes, dystrobrevin-binding protein 1 gene (DTNBP1) located on chromosome 6q22.3 has been associated with schizophrenia in diverse populations." (PMID 27895608, 2016). "The association of gene encoding dysbindin-1 protein (DTNBP1) with schizophrenia has been repeatedly reported in multiple independent case-control studies." (PMID 27462430, 2015). "As a schizophrenia susceptibility gene, DTNBP1 risk polymorphisms and haplotypes are associated with negative symptoms, cognition decline, early visual processing deficits and prefrontal brain function impairment in schizophrenia patients." (PMID 27462430, 2015). "Imaging studies have shown that rs2619528 in DTNBP1 is associated with reduced brain volume and regional cortical thickness in patients with schizophrenia." (PMID 27462430, 2015). "Dystrobrevin-binding protein 1 (DTNBP1), a gene encoding dysbindin-1, has been identified as a susceptibility gene for schizophrenia." (PMID 26171858, 2015). "The DTNBP1 mRNA expression data from immortalized lymphocytes of schizophrenia appear to be rather inconsistent, but a number of studies suggest that reduced dysbindin-1 expression or function is likely to be associated with schizophrenia." (PMID 27462430, 2015). "DTNBP1 has been implicated as a risk factor for psychiatric disorders such as schizophrenia, therefore we examined behavioral responses to acute treatment with METH and PCP in Dys1A-Tg mice." (PMID 25298178, 2014). "Genetic variations in the human dysbindin-1 gene (DTNBP1) have been shown to be associated with schizophrenia, bipolar disorder, and methamphetamine (METH) psychosis, as well as neurocognitive functions in healthy subjects." (PMID 25298178, 2014). "DTNBP1 is one of the most established susceptibility genes for schizophrenia, and hippocampal volume reduction is one of the major neuropathological findings in this severe disorder." (PMID 22580710, 2013). "One of the most replicated susceptibility genes for schizophrenia is the dysbindin-1 gene (DTNBP1; OMIM *607145) on chromosome 6p22.3." (PMID 22580710, 2013). "Findings from a subsequent study indicated that reduction in DTNBP1, frequently observed in schizophrenia, was linked to glutamatergic alterations in intrinsic hippocampal formation connections." (PMID 23618463, 2013). "The secondary analyses instead confirmed effects of the DAO, PPP3CC, and DTNBP1 genes on schizophrenia susceptibility; these effects were mediated not only by the gender and paranoid/non-paranoid dichotomy but also by epistatic/interaction mechanisms." (PMID 23497497, 2013). "Since then (and even before), numerous investigations have been realized to verify the role of DTNBP1 as a schizophrenia susceptibility gene." (PMID 22580710, 2013).
schizophrenia (continued). "Dystrobrevin binding protein 1 (DTNBP1) risk allele has also been associated with regional cortical thinning in temporal brain regions within a study of 62 patients with schizophrenia and 42 healthy controls." (PMID 24386483, 2013). "A meta-analysis authored by Li & He in 2007 only found a weak association of DTNBP1 with schizophrenia." (PMID 22580710, 2013). "The relationship of visual sensory deficits to genetic liability was further emphasized in a pair of studies linking them to specific risk haplotypes for schizophrenia on the dysbindin gene (DTNBP1) and the nitric oxide synthasase-1 gene (NOS1)." (PMID 24381563, 2013). "Several lines of evidence from linkage, association, and postmortem brain studies have indicated an association between DTNBP1 and schizophrenia." (PMID 24168225, 2013). "There is consequently escalating interest in understanding the role of DTNBP1 variants and of its encoded protein in pathophysiology of schizophrenia." (PMID 21390302, 2011). "Twenty studies on populations across the globe report significant associations between schizophrenia and one or more DTNBP1 SNPs and/or haplotypes." (PMID 21390302, 2011). "The dysbindin-1 gene (dystrobrevin-binding protein 1) was originally identified as a gene associated with schizophrenia through its linkage to chromosome 6p." (PMID 21267465, 2011). "An increasing number of studies report associations between variation in DTNBP1, a top candidate gene in schizophrenia, and both the clinical symptoms of the disorder and its cognitive deficits." (PMID 21390302, 2011). "DTNBP1 encodes dysbindin-1, reduced levels of which have been found in synaptic fields of schizophrenia cases." (PMID 21390302, 2011). "The positive association of schizophrenia with DTNBP1 has been replicated in independent studies, but association with the MRDS1/OFCC1 gene has not been tested in other ethnic populations." (PMID 22242126, 2011). "Reduced DTNBP1 mRNA expression in cerebral cortex has been associated with risk haplotypes for schizophrenia." (PMID 20615259, 2010). "In order to identify a common molecular mechanism of disease etiology, DTNBP1 SNP, rs9370822, was chosen for analysis in a number of psychiatric conditions as we found it to be significantly associated with schizophrenia in a previous study." (PMID 20615259, 2010). "A number of studies have found associations between dysbindin (DTNBP1) polymorphisms and schizophrenia." (PMID 20615259, 2010). "The DTNBP1 polymorphism identified in this study is possibly involved in psychiatric liability not only for schizophrenia but also for addictive and anxiety disorders." (PMID 20615259, 2010). "Linkage studies first identified DTNBP1 as a region of high schizophrenia susceptibility and polymorphisms in DTNBP1 have since been identified to be associated with schizophrenia." (PMID 20615259, 2010). "In a previous study, we found a polymorphism in DTNBP1 (rs9370822) that was strongly associated with schizophrenia." (PMID 20615259, 2010). "One of the PPI positives corresponds to a region of human chromosome 6p which includes DTNBP1, a gene implicated in schizophrenia." (PMID 19370154, 2009). "DTNBP1 has been recognized as a schizophrenia susceptible gene, and its protein product, dysbindin-1, is down-regulated in the brains of schizophrenic patients." (PMID 19142223, 2009). "Memory function, one of the representative neurobiological traits related to the risk for developing schizophrenia, was also associated with genetic variations in DTNBP1." (PMID 18945333, 2008). "The dystrobrevin-binding protein 1 (DTNBP1: dysbindin-1) gene is a major susceptibility gene for schizophrenia." (PMID 18945333, 2008). "As the behavioral level, a genetic variation of DTNBP1 was reported to influence general cognitive ability and to be associated with cognitive decline in schizophrenia." (PMID 18945333, 2008).